CDH11 (cadherin 11)
Diseases named in the same sentence as CDH11 in open-access papers (continued):
Sharing a sentence is not in itself a finding about the gene and the disease.
colorectal cancer (7 papers, 2012 to 2024). A primary or metastatic malignant neoplasm that affects the colon or rectum. "CDH11 in association with lactic acid, a key metabolite of the Warburg effect, is, however, implicated in the metastatic progression of colorectal cancer." (PMID 36233808, 2022). "CDH11, which belongs to the cadherin family, induced apoptosis and inhibited cell proliferation by arresting the cell cycle at the G0/G1 phase in colorectal cancer cell lines." (PMID 33407832, 2021). "During the analyses, we set pancreatic and colorectal cancers as controls and discussed the relationships between CDH11 and different clinical characteristics of patients with tumors." (PMID 32685527, 2020). "Data obtained from TIMER and GEPIA showed similar results, with high levels of CDH11 expression shown to be more common in adenocarcinoma like breast, gastric, pancreatic, and colorectal cancers, while lower expression mainly existed in tumors of the urinary and respiratory systems." (PMID 32685527, 2020). "CDH11 exhibited lower expression after S100A4 silencing in colorectal cancer cells, suggesting that it may correlate with S100A4." (PMID 22200787, 2012).
liver fibrosis (7 papers, 2019 to 2022). "Recent studies have also confirmed that cadherin-11 contributes to liver fibrosis caused by carbon tetrachloride and that the level of cadherin-11 correlates with the fibrosis stage." (PMID 35359592, 2022). "There are no reliable diagnostic biomarkers and effective therapeutic drugs for liver fibrosis, however, more and more studies have been focused on the effect of CDH11 in the pathogenesis of liver fibrosis 72-74." (PMID 33442417, 2021). "Together these data demonstrate that CDH11-/- deficient mice have markedly attenuated liver fibrosis compared to WT mice in the CCL4 mice model." (PMID 31269038, 2019). "Wild type (WT) and CDH11 deficient (CDH11-/-) mice were treated with CCl4 or vehicle control for 8 weeks to induce liver fibrosis." (PMID 31269038, 2019). "Furthermore, compared to WT mice, CDH11 deficient mice develop significantly less liver fibrosis when administered CCL4." (PMID 31269038, 2019). "Numerous studies have shown that CDH11 is expressed on a variety of cells in liver fibrosis, including macrophages, injured hepatocytes and HSCs." (PMID 33442417, 2021). "In conclusion, the current manuscript highlights the importance of CDH11 in the development of liver fibrosis." (PMID 31269038, 2019). "In another study, cadherin-11 (CDH11) was increased during liver fibrosis suggesting this protein as an important regulator during liver fibrosis." (PMID 31849997, 2019). "Accordingly, CDH11-/- mice had significantly less histological evidence of liver fibrosis compared to WT mice using Ishak scoring of H&E stained sections." (PMID 31269038, 2019). "In the current report, the extent to which CDH11 modulates the development of liver fibrosis induced by carbon tetrachloride (CCL4) was assessed." (PMID 31269038, 2019). "Interestingly, CDH11-/- mice had decreased histological evidence of liver fibrosis, collagen deposition, α-smooth muscle actin (α-SMA) accumulation, and mRNA levels of fibrotic mediators such as Col1-α1, Snail, TGF-β and IL-6." (PMID 31269038, 2019). "However the expression of CDH11 on other cells, including injured hepatocytes, HSCs and macrophages, during the development of liver fibrosis suggests roles for CDH11 beyond that of regulating myofibroblasts." (PMID 31269038, 2019). "Given common pathways involved in fibrosis in multiple organs, we hypothesized that CDH11 expression is increased during liver injury and contributes to the development of liver fibrosis induced by carbon tetrachloride (CCl4)." (PMID 31269038, 2019). "Together, these data demonstrate that CDH11-/- mice have decreased liver fibrosis induced by CCL4." (PMID 31269038, 2019). "Therefore, CDH11 may be a central player in the development of liver fibrosis through regulation of multiple key cells in fibrogenesis including hepatocytes, HSC, macrophages and myofibroblasts." (PMID 31269038, 2019). "Therefore, CDH11 could be a potential therapeutic target of macrophages for the treatment of liver fibrosis." (PMID 31849997, 2019). "The central hypothesis tested is that CDH11 is an important mediator of liver fibrosis." (PMID 31269038, 2019). "The current report now shows that CDH11 expression is also increased in fibrotic livers of mice treated with CCL4 and CDH11 modulates the development of liver fibrosis." (PMID 31269038, 2019). "CDH11 has been shown to regulate EMT in alveolar epithelial cells and cancer cells, therefore, the expression of CDH11 on HSC and injured hepatocytes suggests that CDH11 may regulate EMT during liver fibrosis." (PMID 31269038, 2019). "The mechanisms of how CDH11 regulates liver fibrosis were not addressed in this report." (PMID 31269038, 2019).
osteoarthritis (7 papers, 2012 to 2025). A noninflammatory degenerative joint disease occurring chiefly in older persons, characterized by degeneration of the articular cartilage, hypertrophy of bone at the margins and changes in the synovial membrane. "Cadherin-11, in particular, has been previously associated with increased migration and invasive capacity of fibroblast-like synoviocytes, a cell population involved in osteoarthritis cartilage degradation." (PMID 35088088, 2022). "In the meantime, we aimed to examine the potential therapeutic effect with PI3K/Akt inhibitor and anti-Cadherin-11 antibody in collagenase-induced osteoarthritis (CIOA) mice." (PMID 31829201, 2019). "Recently, other studies demonstrate that cadherin-11 involves in synovitis and increases the migratory and invasive capacity of fibroblast-like synoviocytes of osteoarthritis." (PMID 26771387, 2016). "Soluble cadherin-11 extracellular fragments were detected in human synovial fluid at significantly higher levels in RA samples compared to osteoarthritis (OA) samples." (PMID 25975695, 2015). "We found that shed soluble cadherin-11 extracellular domains (sCad11) are readily detected in joint synovial fluid and are increased in RA compared to osteoarthritis (OA) synovial fluid." (PMID 25975695, 2015). "The Cadherin-11 and PI3K/Akt pathway are increasingly recognized as the potential therapeutic target of osteoarthritis (OA) synovitis." (PMID 31829201, 2019). "One fibroblast subset, characterized by the expression of proteins podoplanin, THY1 membrane glycoprotein and cadherin-11, but lacking CD34, is threefold expanded in patients with RA relative to patients with osteoarthritis." (PMID 29476097, 2018).
lung carcinoma (6 papers, 2015 to 2022). "This study also revealed several up-regulated genes associated with lung cancer such as TOP2A and MKI67, and with tumor metastasis such as CDH11 and CD44." (PMID 34492061, 2021). "Although ADAM10 mediated cadherin-11 cleavage in mouse embryonic fibroblasts and human lung cancer cells, inhibitor and short-interfering RNA (siRNA) studies indicate that the synovial fibroblast sheddase activity is ADAM- and metalloproteinase-independent." (PMID 25975695, 2015). "Functional classification analysis revealed that lung cancer-related genes, such as TOP2A and MKI67, and tumor metastasis-related genes, such as CDH11 and CD44, were significantly up-regulated after 8 weeks of PHMG exposure." (PMID 33737587, 2021). "Meanwhile, at 8 weeks after PHMG exposure, lung cancer-related genes such as TOP2A and MKI67 and tumor metastasis-related genes such as CDH11 and CD44 were significantly upregulated." (PMID 33737587, 2021). "In this study, we found that ADAM 10 can cleave cadherin-11 on MEFs and a lung cancer cell line, but show it does not cleave cadherin-11 on several types of primary human fibroblasts, despite detectable ADAM10 expression in these cells." (PMID 25975695, 2015).
lymph node metastasis (6 papers, 2012 to 2024). "Furthermore, elevated Cadherin-11 was found in human PCa bone metastasis relative to lymph node metastasis, indicating cadherin-11 is specifically associated with bone metastasis." (PMID 25566502, 2014). "This study also revealed that patients with higher CDH11 levels showed a higher incidence of perineural invasion and lymph node metastasis." (PMID 37013637, 2023). "The positive expression rates of the CDH11 protein in the OSCC patients with lymph node metastasis were 62.16% (N1) and 60.87% (N2) (23/37; 14/23) respectively, which were obviously higher than those in the OSCC patients without lymph node metastasis (N0) (26.09%; 6/23) (p < 0.05)." (PMID 37013637, 2023). "CDH11 CpG island hypermethylation was mostly restricted to the lymph node metastasis." (PMID 22374749, 2012).
systemic sclerosis (6 papers, 2014 to 2024). A chronic disorder, possibly autoimmune, marked by excessive production of collagen which results in hardening and thickening of body tissues. "Cadherin-11 mRNA transcripts have been identified in the peripheral blood, reflecting viable cells in patients with RA and systemic sclerosis (SSc)." (PMID 39211026, 2024). "It was found that the expression of cell adhesion molecules such as cadherin-11 (CDH11) on dermal fibroblasts is elevated in the skin of patients suffering from systemic sclerosis or scleroderma." (PMID 35892569, 2022). "It has been observed that the expression of cadherin-11 (CDH-11) is higher than normal in the skin of patients with systemic sclerosis or scleroderma, which are autoimmune diseases clinically manifesting as progressive fibrosis of the skin and internal organs." (PMID 36267456, 2022). "The expression of CDH11 on dermal fibroblasts is elevated in the skin of patients suffering from systemic sclerosis or scleroderma, which are chronic autoimmune diseases clinically manifesting as progressive fibrosis of the skin and internal organs." (PMID 31963533, 2020). "Furthermore, inhibitory anti-CDH11 monoclonal antibody decreased dermal thickness and fibrotic mediators in the bleomycin-induced dermal fibrosis model and in a mouse model of systemic sclerosis called the tight-skin mouse." (PMID 31963533, 2020). "This interest was stimulated by observations that cadherin-11 is expressed on multiple fibroblast populations, including dermal and lung fibroblasts, and two independent microarray studies of systemic sclerosis skin biopsies demonstrated increased cadherin-11 mRNA levels in fibrotic skin." (PMID 24917820, 2014).
colon cancer (5 papers, 2014 to 2023). "CDH11 has been reported to be associated with increased metastatic ability of breast, prostate and colon cancers." (PMID 25938545, 2015). "Eight significantly over‐expression genes in tumour tissues (BGN, THBS2, SPARC, CDH11, MFAP2, MMP11, SPP1 and THY1) were defined as significantly signature genes that implicated in colon cancer metastasis progress." (PMID 36377223, 2022). "Five genes (BGN, THBS2, SPARC, CDH11 and SPP1) were initially identified as potential biomarkers and therapeutic targets of colon cancer metastasis." (PMID 36377223, 2022). "Comparative proteomic analysis of murine CAFs isolated from sporadic colon cancer with their matched normal fibroblasts revealed upregulation of latent transforming growth factor beta binding protein 2 (LTBP2), farnesyl diphosphate synthase (FDPS), and cadherin 11 (CDH11) in CAFs." (PMID 29280568, 2018).
metastatic carcinoma (5 papers, 2009 to 2022). A carcinoma which has spread from the original site of growth to another anatomic site. "To demonstrate the transcriptional silencing of CDH11 in metastatic cancer cells in association with the presence of CpG island hypermethylation, we measured CDH11 mRNA and protein levels by quantitative RT–PCR (qRT–PCR) and western blot, respectively." (PMID 22374749, 2012). "Once we had observed the CpG island hypermethy- lation-associated silencing of CDH11 in metastatic cancer cells, we sought to demonstrate that the epigenetic inactivation of this gene contributed to metastasis formation." (PMID 22374749, 2012). "In these cancers cadherin-11 expression is associated with the most aggressive and most metastatic cancer cells." (PMID 19274078, 2009). "CDH11 was also known as one of the mediators that interacted with malignant cells and normal cells and was detected in various cancers, especially in metastatic cancer cell lines." (PMID 36315446, 2022). "In the adult, cadherin-11 is strongly expressed in bone as well as certain metastatic cancers, particularly those inclined to metastasize to bone." (PMID 19274078, 2009). "There are five genes (BGN, THBS2, SPARC, CDH11 and SPP1) in metastatic cancer tissues that are significantly higher than non‐metastatic cancer tissue at the transcriptomics level, while only BGN and THBS2 were significant difference in protein expression between metastatic and non‐metastatic cases." (PMID 36377223, 2022).
ovarian carcinoma (5 papers, 2013 to 2023). A malignant neoplasm originating from the surface ovarian epithelium. "Consistent with this notion, an N to E-cadherin switch occurs in ovarian cancer while the expression of cadherin 11 has been shown to suppress cell migration." (PMID 23359820, 2013).
colitis (4 papers, 2014 to 2024). Inflammation of the colon. "In a dextran sodium sulfate-colitis mouse model, CDH11 deficient mice are significantly protected from severe colitis compared to wild-type mice." (PMID 25546151, 2014). "The therapeutic potential of targeting CDH11 was shown in a DSS-induced fibrosis model of colitis in Cdh11 knockout mice." (PMID 38179052, 2023). "Additional studies demonstrated that CDH11 KO mice produced less collagen and developed decreased colitis-driven intestinal fibrosis compared to controls." (PMID 40226415, 2023). "For example, an analysis based on single-cell sequencing found that regulating the activity of CDH11 may affect the production of ECM by MF, thereby alleviating intestinal fibrosis, which is also consistent with previous results in a mouse model of colitis." (PMID 39502647, 2024).
Ewing sarcoma (4 papers, 2024 to 2025). A small round cell tumor that lacks morphologic, immunohistochemical, and electron microscopic evidence of neuroectodermal differentiation. "In Ewing sarcoma, Cadherin-11 (CDH11) and LGR5 have been demonstrated to enhance WNT/β-catenin signalling through stabilisation of β-catenin." (PMID 40983796, 2025). "Ewing sarcoma cells predominantly express β-Catenin on the cell membrane bound to CDH11, which can respond to exogenous Wnt ligands leading to the immediate activation of Wnt/β-Catenin signaling within a tumor." (PMID 38875295, 2024). "Overall, these findings indicate that the highly expressed β-Catenin in Ewing sarcoma directly binds and localizes with CDH11." (PMID 38875295, 2024). "Here, we further report our investigation into Wnt signaling heterogeneity within Ewing sarcoma tumors, which are potentially regulated by the expression of Cadherin-11." (PMID 38875295, 2024). "Here, we demonstrate that CDH11 in Ewing sarcoma functions not only as an adhesion molecule, but also as a key regulator of Wnt ligand responsiveness, a key contributor to metastatic progression." (PMID 38875295, 2024). "In this study, we demonstrate that in Ewing sarcoma cells, β-Catenin expression is dependent on CDH11 expression, and the robust activation of the Wnt/β-Catenin pathway is partially reliant on CDH11." (PMID 38875295, 2024). "Our data suggests that CDH11 is a key regulator of Wnt ligand response in ES cells, and can be a potential anti-metastasis therapeutic target for Ewing sarcoma patients." (PMID 38875295, 2024). "Considering that β-catenin is the driver of canonical Wnt signaling, we further investigated whether CDH11 depletion can affect canonical Wnt signaling in Ewing sarcoma cells." (PMID 38875295, 2024). "Our findings strongly indicate that CDH11 is a key component of regulating Wnt//β-Catenin signaling heterogeneity within Ewing sarcoma tumors, and is a promising molecular target to alter Wnt//β-Catenin signaling in Ewing sarcoma patients." (PMID 38875295, 2024). "Based on our earlier findings that demonstrated β-catenin depletion leads to decreased colony formation, and metastasis in Ewing sarcoma cells, next, we tested whether CDH11 depletion can also lead to decreased metastatic propensity." (PMID 38875295, 2024). "A more recent surfaceome analyses revealed many new Ewing sarcoma cell surface targets including ENPP1 and CDH11 in addition to known IL1RAP, STEAP1, ADGRG2 and CD99, providing newer cell surface targets for immunotherapeutic application in Ewing sarcoma." (PMID 40442778, 2025). "To our surprise, we discovered that Ewing sarcoma cells do not express traditional adherens junction proteins E-Cadherin nor N-Cadherin, but highly express CDH11, a bone Cadherin." (PMID 38875295, 2024).
glaucoma (4 papers, 2020 to 2025). Increased pressure in the eyeball due to obstruction of the outflow of aqueous humor. "Another high-effect SNP was rs1874459 located in an intron of CDH11 on chromosome 16, a locus implicated by multiple GWASs for glaucoma." (PMID 36277849, 2022). "Glaucoma TM tissue has excess ECM so we investigated CDH11 protein levels in normal and glaucomatous TM cells." (PMID 35573666, 2022). "Thus, CDH11 is upregulated in glaucoma TM cells, but mechanical stretch does not appear to additionally affect expression levels." (PMID 35573666, 2022).
head and neck cancer (4 papers, 2012 to 2023). A primary or metastatic malignant neoplasm affecting the head and neck. "CDH11 expression was correlated with angiogenesis and quiescence in a cell subpopulation of head and neck cancer cells, suggestting the importance of CDH11 during carcinogensis by regulating these two single-cell functional states." (PMID 37013637, 2023). "Further, suppressing CDH11 expression can exacerbate the proliferation and invasion of head and neck cancer cells." (PMID 30828336, 2019). "Finally, we also analysed the expression of the CDH11 protein by immunohistochemistry in eight head and neck cancer samples corresponding to the studied paired primary tumour/metastasis of four patients." (PMID 22374749, 2012).
melasma (4 papers, 2016 to 2022). "Loss or decreased expression of miR-675 has been shown to occur in melasma, and is associated with the regulation of its target cadherin 11 (CDH11)." (PMID 28430163, 2017). "TheWNT3A, EDN3, ESR2, PTG2, MMP1, and SOD2 genes were up-regulated, whereas the COL4A1, CSF2, DKK3, COL7A1, TIMP4, CCL2, and CDH11 genes were down-regulated in melasma skin fibroblasts when compared to the ones from adjacent healthy skin." (PMID 35840442, 2022). "In skin fibroblasts, CDH11 regulates collagen and elastin synthesis, and its down-regulation can influence a decrease in dermal repair in melasma skin." (PMID 35840442, 2022).
renal cell carcinoma (4 papers, 2014 to 2023). "In renal cell carcinoma, CDH11 expression enhanced cell motility and induced high levels of bone metastasis due to the high affinity of homotypic interactions with native osteoblasts." (PMID 37558205, 2023).